OR51H1 (olfactory receptor family 51 subfamily H member 1)
Description:
Odorant receptor.
Synonyms: formerly OR51H1P
Gene: Transcribed unprocessed pseudogene on chromosome 11 (4,859,617 to 4,860,564, reverse strand). Ensembl gene ENSG00000176904.
Subcellular location: Cell membrane
Pathways (Reactome):
Sensory Perception: Expression and translocation of olfactory receptors